OR6J1 (olfactory receptor family 6 subfamily J member 1)
Description:
Odorant receptor.
Synonyms: OR6J2; OR6J1P
Tractability: Antibody: UniProt places it where antibodies can reach, with medium confidence; UniProt predicts a signal peptide or a membrane-spanning region; its Gene Ontology location is reachable by antibodies, with medium confidence.
Gene: Protein-coding gene on chromosome 14 (22,630,929 to 22,644,352, reverse strand). Ensembl gene ENSG00000255804.
Subcellular location: Cell membrane
Pathways (Reactome):
Sensory Perception: Expression and translocation of olfactory receptors
Gene Ontology:
Molecular function: olfactory receptor activity; G protein-coupled receptor activity
Biological process: detection of chemical stimulus involved in sensory perception of smell; G protein-coupled receptor signaling pathway
Cellular component: plasma membrane; membrane
Homologues: Orthologues: pig OR6J1 (86% identical). Paralogues in human: OR6M1 (50% identical), OR6S1 (46% identical), OR6T1 (45% identical), OR6C4 (44% identical), OR6F1 (44% identical), OR6C76 (42% identical), OR6C65 (41% identical), OR6C74 (41% identical), OR6C75 (41% identical), OR2AP1 (41% identical), OR6C3 (41% identical), OR6C70 (41% identical), and 6 more.